ENSG00000284874 (novel transcript)
Synonyms: SEPT5-GP1BB
Gene: Protein-coding gene on chromosome 22 (19,717,220 to 19,724,772, forward strand). Ensembl gene ENSG00000284874.
Genetic constraint (gnomAD): Missense variants: 381 observed, 510.77 expected, observed/expected ratio (o/e) 0.75, 90% interval 0.69 to 0.81. Synonymous variants: 210 observed, 197.78 expected, observed/expected ratio (o/e) 1.06, 90% interval 0.95 to 1.19.